EPO (erythropoietin)
Diseases named in the same sentence as EPO in open-access papers (continued):
Sharing a sentence is not in itself a finding about the gene and the disease.
anemia (continued). "In mice, 32-134D inhibits intratumoral EPO expression but does not affect serum EPO levels and does not cause anemia over a 2-week treatment course." (PMID 35499076, 2022). "In addition, the widespread use of erythropoietin to treat anemia in chronic kidney disease contributes to fewer transfusion practice and, consequently, decreased risk of HCV transmission." (PMID 36618760, 2022). "Similarly, in a cross-sectional study of patients with CKD not on dialysis in China, approximately one-third of patients with anemia were receiving treatment with erythropoietin and/or iron products." (PMID 35490226, 2022). "Furthermore, a relationship between IS and CKD-related anemia has been observed since it diminishes erythropoiesis, hampers the activity of erythropoietin, and enhances the programmed cell death of red blood cells (eryptosis)." (PMID 36145188, 2022). "Although anemia was common, only a small number of patients received supportive therapies for anemia during the 6-month period after initiation of a new core management strategy, with 9 patients receiving erythropoietin and 1 patient receiving danazol." (PMID 35371428, 2022). "Chronic inflammation and persistent activation of the immune system may lead to anemia, likely due to insufficient production of erythropoietin and the decreased response of erythroid progenitors." (PMID 36553200, 2022). "The etiologies of anemia in HF patients are multifactorial and heterogeneous, including inadequate erythropoietin levels due to renal dysfunction, hemodilution, hematinic deficiencies such as iron deficiency, bone marrow dysfunction, inflammation, and medications." (PMID 35600475, 2022). "Erythropoietin (EPO) is known as a hormone for erythropoiesis in response to anemia and hypoxia." (PMID 35806148, 2022). "Erythroid progenitor cells of newborns are responsive to EPO in vitro, suggesting that inadequate EPO production is a significant cause of neonatal anemia, not unresponsiveness of marrow." (PMID 35740728, 2022). "Anemia of CKD is caused by multiple factors and is mainly the result of the impaired kidney being unable to adequately respond to hypoxia and/or anaemia by inducing erythropoietin (EPO) production." (PMID 35359863, 2022). "Among potential therapeutic agents for anemia in patients with CKD are those that induce endogenous EPO production, thereby avoiding high transient plasma concentrations of ESAs that may occur with intravenous administration." (PMID 35751858, 2022). "Iron and erythropoietin are the main stay of treatment for anaemia in ESRD patients." (PMID 36233647, 2022). "Finally, inflammatory cytokines such as interleukin-1 and tumour necrosis factor-α inhibit erythropoietin expression and increase erythrophagocytosis, thus also contributing to eventual anemia." (PMID 35508964, 2022). "Ineffective erythropoiesis and peripheral hemolysis lead to severe anemia, tissue hypoxia, and a reactive production of erythropoietin (EPO) with a consequent compensatory increase of the number of bone marrow erythroblasts and extramedullary hematopoiesis with characteristic hepatosplenomegaly." (PMID 34207028, 2021). "In addition to produce EPO under conditions of anemia and hypoxia, pericytes produce growth factors to promote angiogenesis or microvascular stability." (PMID 34724959, 2021). "It remains unclear if and how bile acid toxicity induces anemia of chronic disease leading to the increase in EPO and FGF23." (PMID 34362888, 2021). "A possible conclusion from the observation that eGFR was not strongly associated with anemia is that AP influenced eGFR and not the other way around, as acute kidney injury is expected to increase plasma erythropoietin concentration." (PMID 34485326, 2021).
anemia (continued). "It is widely acknowledged that low grade inflammation and chronic disease is associated with anaemia and that several pro-inflammatory cytokines, such as IL-6 and tumor necrosis factor-α (TNF-α) could inhibit erythropoiesis and the actions of erythropoietin." (PMID 33781199, 2021). "However, when the erythropoietic response is insufficient to rescue anemia, EPO is produced constantly." (PMID 33669537, 2021). "Furthermore, erythropoiesis-stimulating agents (ESA), such as high dose erythropoietin (EPO), play a key role in patients with symptomatic anemia needing regular transfusions." (PMID 34300079, 2021). "The study (NCT01147666) was a two-part study and included hemodialysis-treated anemia and terminal renal failure patients who had previously received erythropoietin and intravenous iron for 4 weeks prior to randomization, showing an average Hb level of 9–13.5 g/dL for 8 weeks." (PMID 33567688, 2021). "It will be of interest to learn whether some of these small molecules that specifically enhance HIF‐2α function can replace recombinant EPO in the long‐term treatment of anemia." (PMID 33475252, 2021). "TNF-α contributes to anemia by inhibiting erythropoietin secretion and/or through direct toxicity on erythroid precursor cells, while interleukin-6 induces the production of hepcidin, which binds to ferroportin, thereby blocking the intestinal absorption of iron." (PMID 34071554, 2021). "Therefore, it transpires that SGLT2 enhances erythropoietin (EPO) secretion which subsequently raises hematocrit levels in patients with severe anemia." (PMID 34545553, 2021). "In CKD patients, EPO levels are inadequately low with respect to the degree of anemia." (PMID 33842503, 2021). "Anemia can be attributed to the insufficiency of unresponsiveness of EPO." (PMID 33461597, 2021). "Furthermore, Roxadustat transiently increased endogenous EPO plasma levels within or near the physiological range in patients with anemia due to CKD." (PMID 34830468, 2021). "Using a PHD inhibitor, Roxadustat, in these patients allow HIFs to accumulate and, thus, enhance EPO secretion and normalize Iron homeostasis, breaking the vicious cycle of anemia that affects other CV organs and increase the morbidity and mortality rate in such patients." (PMID 34447792, 2021). "EPO continues to surprise us as it goes beyond erythropoiesis as a very valuable agent, not only for the treatment of anemias of different etiology, but also as a survival/protection factor useful for the development of ATMPs derived from human MSCs and/or other tissue stem cells." (PMID 34440909, 2021). "Treatment of anemia using erythropoietin stimulating agents is the mainstay." (PMID 34718902, 2021). "Anemia in SARS‐CoV‐2 infection may be related to cytokine‐induced inhibition of erythropoietin formation and can lead to an increased requirement for mechanical ventilation in critically ill patients." (PMID 34226901, 2021). "Insufficient EPO production leads to anemia in patients with chronic kidney disease." (PMID 34724959, 2021). "HIF-2α is crucial for the induction of erythropoietin; ablation of HIF-2α in mice leads to anemia due to inadequate production of renal EPO, in addition, the location of renal EPO-producing cells coinciding with the location of renal interstitial HIF-2α-expressing cells." (PMID 34356833, 2021). "Moreover, the combination of severe anemia resulting from ineffective erythropoiesis with substantial tissue hypoxia stimulates the production of erythropoietin (EPO) to a greater extent compared with normal controls." (PMID 34575839, 2021). "Our previous study indicated that erythropoietin treatment for severe anemia could decrease the incidence of NEC in preterm infants, which indirectly proves the association between severe anemia and NEC." (PMID 34283868, 2021). "Importantly, the administration of EPO in doses required to correct anemia resulted in increased frequency of peripheral Treg in humans with CKD." (PMID 33796104, 2021).
anemia (continued). "Erythropoietin-resistant anemia will necessitate higher EPO doses if underlying causes are not adequately treated." (PMID 34718902, 2021). "Increased plasma FGF23 and EPO levels are often observed in anemia." (PMID 34362888, 2021). "Therefore, several interventions to modify pre-operative anemia have been developed, such as oral and intravenous iron supplements and as well as recombinant human erythropoietin." (PMID 34436045, 2021). "Some of these patients may have polycythemia resulting from cystic production of erythropoietin hence preventing anemia progression." (PMID 33910506, 2021). "Recombinant human erythropoietin is used to treat anemia in CKD patients." (PMID 34059008, 2021). "In cancer, EPO is secreted predominantly in response to tissue hypoxia resulting from anemia." (PMID 33669537, 2021). "In addition, NSAIDs can blunt the production of erythropoietin resulting in anemia, since hemoglobin synthesis depends on this hormone." (PMID 34577072, 2021). "Furthermore, EPO production is insufficient in response to anemia, with a mild impact of EPO on erythropoiesis." (PMID 34984131, 2021). "The primary mechanism related to anemia in CKD dogs is decreased renal production of EPO." (PMID 34209294, 2021). "Proinflammatory cytokines are responsible for various processes typical of anemia of chronic diseases—they suppress erythropoiesis in the bone marrow, impair the production of erythropoietin (EPO) and increase the rate of erythrophagocytosis leading to shorter erythrocyte lifespan." (PMID 33025407, 2021). "Furthermore, β-adrenergic mechanisms regulate erythropoiesis in erythropoietin-resistant anemia and in resultant anemia after severe injury." (PMID 34063503, 2021). "Reduced RBCs could lead to anemia and hypoxia that stimulate erythropoietin (EPO) production to induce erythropoiesis." (PMID 33954177, 2021). "Rodent studies suggest that the EPO response to hypoxia is markedly reduced in newborn compared to adult rats, possibly because the high oxygen-affinity fetal hemoglobin mitigates tissue hypoxia due to anemia." (PMID 33995348, 2021). "Alternatively, TNF-α and IL-1 have been shown to inhibit EPO production and therefore the inflammatory environment could suppress EPO production by the fetus during anemia." (PMID 33995348, 2021). "As indicated by Hansson and colleagues, measurement of erythropoietin levels may help to determine the role of anemia relative to tubular injury." (PMID 34836182, 2021). "The total EPO equivalent dose that this case and our 4 patients received, ranged between 10,000 and 20,000 IU (100–200 μg) over 1–5 weeks, corresponding to the conventional dosing for anemia treatment in nephrology (around 2000–4000 IU per injection)." (PMID 34565332, 2021). "A recent study identified that erythropoietin (EPO) could be a potential link between anemia, iron status, and FGF23 production." (PMID 34572066, 2021). "Another randomized clinical trial designed to evaluate the superiority of recombinant human erythropoietin to PRBC transfusion in treating anemia in patients with cervical cancer was halted prematurely owing to concerns regarding increased thromboembolic events with recombinant human erythropoietin." (PMID 33818620, 2021). "Besides the correction of anemia, erythropoietin also has cardioprotective, renoprotective, and neuroprotective functions." (PMID 33628672, 2021). "This situation reflects the initial phase of the anemia that often accompanies diabetes due to the presence of a chronic inflammatory status, and in more advanced phases, the development of kidney disease, affecting the production of EPO." (PMID 33920401, 2021). "In a diabetic patient, the appearance of anemia is favoured by peripheral neuropathy, which could compromise the detection of O2 necessary for the production of EPO." (PMID 34356993, 2021). "Furthermore, anemia in spite of high EPO concentration suggests some mechanism of peripheral hyporesponsiveness in the course of CKD." (PMID 33918412, 2021).
anemia (continued). "Consequent haemorrhage and anaemia can trigger elevated systemic erythropoietin (EPO) levels." (PMID 34831179, 2021). "Furthermore, anemia can occur in patients with chronic kidney disease (CKD) predominantly owing to inappropriately low erythropoietin (EPO) production relative to the degree of anemia." (PMID 34449692, 2021). "Our data introduce Cibinetide as an appealing candidate for the treatment of bone loss either as a stand-alone therapy for osteolytic pathologies ranging from cancer to rheumatoid arthritis and osteoporosis, or in combination with EPO for patients with anemia or cancer." (PMID 35008482, 2021). "For example, INF-γ whose over expression in mice results into anaemia and inhibits erythropoiesis through stem cell factor (SCF) and erythropoietin (EP) could be implicated." (PMID 34284027, 2021). "Anemia is a common complication of certain chronic diseases and can be treated by stimulating hematopoietic cells to increase red blood cell count, and this action is achieved by recombinant human erythropoietin." (PMID 33628672, 2021). "SHP has been associated with resistance to the effects of erythropoietin therapy in patients with CKD-associated anemia; this is defined as failure to normalize hemoglobin after four to six months of erythropoietin therapy in the absence of iron deficiency." (PMID 34408941, 2021). "Therefore, human erythropoietin was overexpressed in the grafts and implanted in a mouse anemia model." (PMID 33738695, 2021). "Reasons for the poor performances of sTfR in our population may be the lack of clear cut-offs, as suggested by other studies, and the fact that sTfR is also influenced by erythropoietin, which may play an important role in severe HIV-associated anaemia." (PMID 32107492, 2020). "Others' studies have also found that anti-EPO antibody prevalence in ESRD patients who receive ESA may be associated with EPO resistance and demand, resulting in anemia." (PMID 32318578, 2020). "The recent research and development of new types of EPO for treatment of anemia and other conditions may increase the applications of EPO for additional conditions." (PMID 32154256, 2020). "However, the present study exclusively enrolled CKD patients who frequently experienced anemia due to a deficit of erythropoietin." (PMID 32066395, 2020). "Subsequently, chronic inflammation can lead to anemia through several pathways, e.g., induction of the master regulator of iron homeostasis hepcidin by Interleukin-6 or the inhibition of erythropoietin formation in the kidney mediated by Interleukin-1 and TNF-alpha." (PMID 32903529, 2020). "This dose of RBV may induce anaemia, which requires erythropoietin (EPO) in 40% of patients and sometimes blood transfusions." (PMID 32677900, 2020). "EPO levels in diabetic chronic kidney disease also serve as an indicator for predicting mortality, and increasing endogenous EPO levels is effective in the treatment of anemia in patients with chronic kidney disease." (PMID 32290638, 2020). "Hence, the beneficial effect of HIF-PHIs in the treatment of anemia is very unique, just like killing two birds with one stone: increasing expression of EPO within the physiological range and promoting iron utilization." (PMID 32869703, 2020). "The endocrine regulation, mediated by erythropoietin, is the most robust and is responsible for the adaptation of the erythroid lineage to various physiological conditions, e.g., high altitude, hypoxia or anemia." (PMID 32471308, 2020). "In agreement with this, our Foxd1Cre::Pdgfrb+/J mice also developed progressive anemia due to reduced production of renal EPO and failed to respond to blood loss, mimicking renal anemia in patients." (PMID 31943786, 2020). "Correction of anemia, in particular among elderly subjects and/or patients with renal insufficiency, may also make use of erythropoietin (EPO)." (PMID 33372616, 2020).
anemia (continued). "Thus, recombinant analogues and derivatives of human erythropoietin used in the treatment of anemia of chronic diseases can promote tumor growth and immortality (including through pro-angiogenic and anti-apoptotic effects)." (PMID 32560029, 2020). "Consequently, our results demonstrated that on-line haemodiafiltration improves anaemia control with reduced erythropoietin doses." (PMID 32994444, 2020). "Erythropoietin (EPO) resistance and iron refractory anemia require red blood cell transfusions." (PMID 32968161, 2020). "Based on the importance of EPO and iron homeostasis in the occurrence and development of anemia in CKD, the roles of JPYS on translational control of HIF-α protein via ERK signaling and iron recycling could be hypothesized." (PMID 33178327, 2020). "Importantly, endogenously high EPO levels, either due to induced anemia or constitutive overexpression of this hormone (both in murine models), also lead to significant bone loss." (PMID 32471308, 2020). "However, differently from anemia, the independent prognostic value of EPO appears to emerge only after post-TAVR recovery is completed." (PMID 33330669, 2020). "Recombinant human EPO is regularly used to prevent or treat anemia of the PTI and studies in patients reveal that the early use of erythropoiesis-stimulating agents may reduce the incidence of GM-IVH and be neuroprotective." (PMID 33043002, 2020). "Anemia is the more frequent cytopenia that could be treated erythropoietin (EPO) stimulating agents (ESA)." (PMID 33686047, 2020). "Anemia with chronic kidney disease shows decreased production of EPO." (PMID 32290638, 2020). "Most osteosarcoma patients have anemia, which can induce high levels of EPO." (PMID 32908942, 2020). "The joint American Society of Clinical Oncology/American Society of Haematology (ASCO/ASH) guidelines recommend an erythropoiesis stimulating agent (ESA) such as recombinant erythropoietin (EPO) or darbopoeitin (DPO) for chemotherapy-induced anemia on treatment where hemoglobin (Hb) < 10 g/dL." (PMID 33081013, 2020). "The subsequent chapters will be dedicated to specific aspects of renal disease and DNA methylation, which are relevant to: (I) anemia and erythropoietin in CKD (II) metabolic and biochemical aspects (e.g., hyperhomocysteinemia (HHcy), a strong cardiovascular risk factor with high prevalence in CKD." (PMID 32708735, 2020). "Endogenous erythropoietin (EPO) levels were also inadequate to the degree of anemia and the patient was treated with steroids and recombinant EPO epoetin alpha 40,000 UI/week and vitamin supplementation with progressive increase of reticulocytes and transfusion independence." (PMID 33261016, 2020). "Although rhEPO could markedly correct anemia, supraphysiologic EPO concentrations achieved during rhEPO treatment may contribute to the adverse cardiovascular effects." (PMID 32869703, 2020). "Moreover, rHuEPO, now collectively known as erythropoietin-stimulating agents (ESAs), includes recently developed long-acting products that have demonstrated significant efficacy in improving anemia, preventing complications, and improving patients’ QOL." (PMID 32998272, 2020). "EPO can improve anemia by inducing erythropoiesis, thus indirectly ameliorating organ damages." (PMID 32154256, 2020). "However, after the removal of the anti-EPO antibody, treating anaemia in these patients with chronic renal disease with EPO therapy is difficult, as restarting EPO therapy risks the recurrence of anti-EPO antibody-mediated PRCA." (PMID 32856389, 2020). "Iron deficiency, inflammation, and EPO have been shown to increase FGF23 levels and cleavage; and conversely, FGF23, particularly in CKD, may promote anemia, iron deficiency, and inflammation." (PMID 33392212, 2020). "Furthermore, aging leads to unexplained anemia, probably due to pathological processes such as progressive resistance of bone marrow erythroid progenitors to erythropoietin and a chronic, subclinical pro-inflammatory state." (PMID 32648135, 2020).